CEACAM6 (CEA cell adhesion molecule 6)
Diseases named in the same sentence as CEACAM6 in open-access papers (continued):
Sharing a sentence is not in itself a finding about the gene and the disease.
cancer (continued). "CEACAM6 KO impacts several hallmarks of cancer including ECM-cell adhesion, transmembrane proteins, metabolism and transport, autophagy, DNA repair, chromatin modifications and signal transduction." (PMID 31797958, 2019). "A receiver-operative characteristic (ROC) analysis of the larger tissue microarray yielded an area under the curve (AUC) of 0.880 for the discrimination of cancer from normal samples by CEACAM6." (PMID 27421133, 2016). "On the contrary, the expression level of the two other candidate markers LGALS4 and CEACAM6 display opposite trends, with higher levels in normal healthy blood compared to cancer blood." (PMID 26993598, 2016). "Many proteins associated with cancer, such as S100A9, MUC 1, NGAL, CEACAM6 and several other biomarkers have been identified in bile in patients with malignant biliary strictures, further suggesting the importance of bile in proteomic analysis." (PMID 25304323, 2015). "In human lung, CEACAM6 is developmentally and hormonally regulated, protects surfactant function, has anti‐apoptotic activity and is dysregulated in cancers." (PMID 26702074, 2015). "CEACAM6 plays an important role in migration, invasion, and adhesion, crucial steps for the metastatic spread of cancer cells to secondary tissue sites other than lymph nodes and potential targets for new therapeutic modalities." (PMID 25427744, 2015). "CEACAM6 acts as an oncogene in tumors and promotes cancer invasion, metastasis, anoikis resistance and chemoresistance, and inhibits differentiation." (PMID 25398131, 2014). "GPI-anchored members, CEA and CEACAM6, show up-regulation in 50–70% of all human cancers, including colon, breast and lung cancers." (PMID 18159236, 2007). "The cases with values of CEACAM6 under 2 in cancer tissues were considered to be a low expression group (n=13), whereas those with values 2 or over were considered to be a high expression group (n=10)." (PMID 16868542, 2006). "CEACAM6 is highly expressed in various human cancer tissues and its clinical significance has been widely reported." (PMID 16868542, 2006). "Increasing evidence implicates CEACAM6 as a determinant of malignant cellular behaviour and clinical outcome in a range of human cancers." (PMID 15316565, 2004). "The immunoglobulin superfamily member carcinoembryonic antigen-related cell adhesion molecule 6 (CEACAM6) is emerging as an important determinant of the malignant phenotype in a range of cancers." (PMID 15316565, 2004). "Thereby, CEACAM6 promoted cancer metastasis by increasing cell migration and invasion abilities." (PMID 39468006, 2024). "We therefore hypothesize that CEACAM6 is a marker for late-stage cancers that are more likely acidic or hypoxic." (PMID 38502695, 2024). "Future studies could test the efficacy of combining L-DOS47 and anti-PD1 or other immunotherapies in additional CEACAM6-expressing preclinical cancer models and clinical trials." (PMID 38398062, 2024). "CEACAM6 overexpression has been observed in other cancer entities but the molecular function remains unclear." (PMID 39468006, 2024). "As CEACAM6 has been less studied in cancer compared to MUC1, we chose CEACAM6 for further studies." (PMID 39468006, 2024). "Alternatively, antibody–drug conjugates (ADCs) targeting CEACAM6 as the cancer-specific antigen and cytotoxic drugs as the cargo, could be developed." (PMID 38502695, 2024). "Furthermore, the CEACAM6 molecule, acknowledged as a prognostic indicator for survival and recurrence in various types of cancer, was also overexpressed in LCH lesions." (PMID 38342891, 2024). "We hypothesize that CEACAM6 induction is a response to acid stress and confers cancer cells with a growth advantage under such conditions." (PMID 38502695, 2024).
cancer (continued). "A majority of CEACAM6 on the surfaces of cancer cells can interact with other members of the CEA family on the surface of cancer cells in an interaction called cross-linking, which results in a significant increase in c-Src kinase activity and caveolin-1 phosphorylation." (PMID 38796667, 2024). "Moreover, we dissect the intricate signaling pathways influenced by CEACAM6, underscoring its potential as a biomarker for cancer diagnosis and prognosis." (PMID 38796667, 2024). "Indeed, both CEACAM5 and CEACAM6 molecules have been reported to be highly overexpressed in multiple types of cancer." (PMID 38279989, 2024). "We propose that a suitable drug delivery system, which targets CEACAM6 or CEACAM5 as markers of acid-resistant cancer cells, could be a promising molecularly stratified therapeutic strategy for CRC." (PMID 38502695, 2024). "As ongoing research continues to unravel the complexities of CEACAM6-mediated signaling, it may pave the way for innovative strategies in cancer treatment and management." (PMID 39767561, 2024). "In this review, we explore current knowledge surrounding CEACAM1, CEACAM5, and CEACAM6, highlight their pathological significance in the areas of cancer biology, immunology, and inflammatory disease, and describe the utility of murine models in exploring questions related to these proteins." (PMID 36741860, 2023). "CEACAM6 is important for the metastatic potential of cancers." (PMID 36741860, 2023). "Although the important roles of CEACAM6 in the cancer metastasis have been conformed in various studies, the exact molecular mechanism underlying the promoting effect of CEACAM6 overexpression on LM is still unclear for the difficulty on the construction of a leptomeningeal metastasis model." (PMID 36082960, 2023). "In addition, a subset of these genes has been associated with cancer therapy responses (AZU1, CDCA3, CEACAM6, EN1, PF4)." (PMID 35008420, 2022). "Although it is not routinely used clinically, the relevance of CEACAM6 as a biomarker has already been well established in the cancer field, where it has invariably been found to be associated with poor prognosis." (PMID 39239252, 2022). "CEACAM6 (CEA-related cell adhesion molecule 6) is a cell adhesion protein of the CEA family and expressed on normal epithelial tissue, and its overexpression is associated with development, invasion, and metastasis of cancer." (PMID 35655198, 2022). "Besides, CEACAM6 expressed on cancer cells can also help enhance the resistance of cancer cells to anoikis." (PMID 36059616, 2022). "In other words, CEACAM6 can maintain the adhesion between cancer cells." (PMID 36059616, 2022). "Finally, the CEACAM6 (carcinoembryonic antigen-related cell adhesion molecule 6) is also overexpressed in several types of cancers, such as colorectal, pancreas, prostate, lung, and breast." (PMID 36016136, 2022). "Furthermore, the CEACAM6 expression in cancer tissues with clinical grades 2, 3, and 4 are much higher than in the normal tissues." (PMID 34221964, 2021). "Top five miRNA binding sites for both CEACAM6 and CEACAM8 and previous cancer associations." (PMID 34447411, 2021). "Blocking CEACAM6’s function with a specific antibody was also shown to reduce cancer growth." (PMID 34359854, 2021). "From the data above, it was showed CEACAM6 was up regulated (P<0.05) in both Dys and Cancer groups." (PMID 34221964, 2021). "CEACAM6 regulates cell adhesion, proliferation, signaling in cancer, and immunity." (PMID 33538227, 2021). "PC 3 cancer cell line, which lacked the necessary CEACAM6 sites, was not susceptible to CEACAM6 antibodies; the results echo this, revealing a minimal reduction in terms of cell viability." (PMID 32357523, 2020). "CEACAM6 overexpression was previously reported in various types of cancer including NSCLC." (PMID 32536039, 2020).
cancer (continued). "Moreover, over-expression of CEACAM6 modulates cancer progression through aberrant cell differentiation, anti-apoptosis, cell growth, and resistance to therapeutic agents." (PMID 31244774, 2019). "Interestingly, several genes associated with cancer cells invasion were downregulated upon HPSE knockdown, including MMP1, MMP7, MMP10, MMP13, and CEACAM6." (PMID 31001480, 2019). "CEACAM6 is also expressed in many human cancers and is observed in the sera of cancer patients." (PMID 25427744, 2015). "CEA and CEACAM6 are immunoglobulin family intercellular adhesion molecules that are up-regulated without structural mutations in approximately 70% of human cancers." (PMID 18159236, 2007). "CEACAM6 also is expressed on granulocytes and epithelia from various organs, and has a broader expression zone in proliferating cells of hyperplastic colonic polyps and adenomas, compared with normal mucosa, as well as by many human cancers." (PMID 17201906, 2007). "Similarly, CEACAM6 is overexpressed in cancers of the colon, stomach, pancreas, lung, breast, and female reproductive system, and in leukemia." (PMID 17576469, 2007). "The fact that CEA and/or CEACAM6 are over-expressed in so many human cancers has led us and others to suggest that this effect could contribute to tumorigenesis." (PMID 18159236, 2007). "Targeting CEACAM5 and/or CEACAM6 may therefore be a novel method of modulating cancer cell chemosensitivity and apoptosis." (PMID 17201906, 2007). "This study, however, utilizing transgenic mice expressing human CEA and CEACAM6 genes with the human tissue specific pattern but with increasing expression levels to the point of those found in human carcinomas, represents perhaps the closest approximation to the human situation yet investigated." (PMID 18159236, 2007). "The reason why CEACAM6 overexpression is associated with aggressive biological behaviour of cancer cells has not been fully clarified." (PMID 16868542, 2006). "Although the function of CEACAM6 in ALL blasts is still unknown, this molecule's function has been recently associated with pathogenesis of other types of cancer in man." (PMID 15826304, 2005). "In addition, CEACAM6 is abundantly overexpressed in a high proportion of cancers." (PMID 38279989, 2024). "Thus, CEACAM6 demonstrated a pivotal role in supporting cell migration by regulating cell adhesion which may promote the initial steps of cancer metastasis in vivo and in vitro." (PMID 39468006, 2024). "The protein target of miR-29a is a carcinoembryonic antigen-related cell adhesion molecule 6 (CEACAM6), a glycoprotein that mediates cell–cell interactions and is involved in cell adhesion, proliferation, migration, invasion, and metastasis and that is overexpressed in a wide variety of carcinomas." (PMID 38545547, 2024). "In addition, CEACAM6 is a useful prognostic tool for cancer." (PMID 36741860, 2023). "Blockade of CEACAM6 reactivated the antitumor response of T cells in a previous study using cell lines, thus CEACAM6 might have something to do with angiogenesis and immunosuppression which is important in the growth of cancer." (PMID 35655198, 2022). "However, how CEACAM6 is associated with drug resistance of cancer cells has not yet been fully clarified." (PMID 32648688, 2020). "Moreover, whether KRAS status or mutations of other cancer driver genes in CRC patients (TCGA database) might have led to lack of CEACAM5 interaction with the other studied genes (CEACAM1, CEACAM6 and EPHA2) will need further investigation." (PMID 29262644, 2017). "All these results revealed that 131I‐tinurilimab has an excellent performance in inhibiting the growth of CEACAM6‐positive xenografts, reflecting its potential therapeutic ability in LUAD or malignant pulmonary nodules." (PMID 40178153, 2025).
cancer (continued). "Remarkably, the group of cancer-related proteins,i.e., CEACAM1,CEACAM5, and CEACAM6 as well as the minichromosome maintenance complexcomponents MCM3, MCM4, and MCM6 showed clear protein abundance patternsrelated to the radiation response." (PMID 40574313, 2025). "DEG analysis revealed higher expression levels of CRC markers such as CEACAM6, SPINK1, TGFBI and RSPO3 in the cancer cell group." (PMID 40355592, 2025). "The results showed that CEACAM6 and CD24 were specifically highly expressed in cancer stem cell (CSC)." (PMID 40860182, 2025). "We identified one cluster as the cancer‐pre cells, since it was enriched in the EGC biopsy and expressed cancer markers (CEACAM5 and CEACAM6)." (PMID 40860436, 2025). "Immunohistochemical analysis revealed that CEACAM6 protein was expressed universally in clinical PDAC, and the expression was restricted to cancer cells." (PMID 38467634, 2024). "The reactivity of NEO-201 on colon, pancreas, lung normal and cancer tissues was compared to the reactivity of commercially available anti-CEACAM-5 and CEACAM-6 mAbs." (PMID 35804808, 2022). "Based on miRDB rankings, the top five microRNAs that bind to the 3′ UTRs of CEACAM6 and CEACAM8 have previous links to cancer; thus, disrupted microRNA binding likely leads to aberrant CEACAM6 and CEACAM8 expression." (PMID 34447411, 2021). "In Elyada’s scRNA-seq analysis, ductal cancer cells in human PDAC were clustered in two major subtypes: the classic (by TFF1, TFF2, LYZ, VSIG2, and CEACAM6 marker genes) and secretory (by SPP1, CLU, CTGF, and COL18A1 marker genes) subtypes." (PMID 34035226, 2021). "By western blotting we found that mAb 6G5j detected endogenously expressed CEACAM1, CEACAM5 and CEACAM6 in lysates of epithelial cell lines derived from gastric (MKN45) and colon (HT29, Caco-2) cancer cell lines." (PMID 32064046, 2020). "A literature search showed that many of these altered genes, such as IGF2, FAM83A, CEACAM5 and CEACAM6, STC1 and MSMP, play a role in PCa or other types of cancer." (PMID 31500347, 2019). "The expression levels of CEACAM6 mRNA, which were corrected for those of GAPDH mRNA, in cancer tissues (5.90±8.74; mean±s.d)." (PMID 16868542, 2006). "While CDH2 and CEACAM6 are known to have elevated expression in various cancers, to the best of our knowledge no clear role or association between DCAF7 and cancer has so far been described." (PMID 41160880, 2026). "Previous research has reported that carcinoembryonic antigen‐related cell adhesion molecule 6 (CEACAM6) was overexpressed in LUAD compared to benign pulmonary nodules, while the specificity of it to distinguish benign nodules from malignant tumor (LUAD) remains to be further clarified." (PMID 40178153, 2025). "Notably, CEACAM6 is a metastasis biomarker, and its inhibition has been shown to improve the sensitivity of LUAD cancer cells to chemotherapy and anoikis." (PMID 41423496, 2025). "EBET-conjugated #84.7 (84-EBET) has lethal effects on various PDAC organoids and bystander efficacy on CEACAM6-negative PDAC cells and cancer-associated fibroblasts." (PMID 38467634, 2024). "CEACAM6 can bind itself or CEACAM1, whether blocking CEACAM6 by antibodies alone is enough to restore the immunity of cancer patients remains to be discussed." (PMID 38796667, 2024). "Previously, the specificity and cytotoxicity of L-DOS47 were confirmed in different CEACAM6-expressing cancer cell lines (BxPC-3 pancreatic, A549 lung, MCF7 breast, and CEACAM6-transfected H23 lung), wherein the response to L-DOS47 was positively correlated with the levels of CEACAM6 expression." (PMID 38398062, 2024). "In the presence of CEACAM6 antibody derived from the hybridoma cell culture extract, the MDA-MB-468 cancer cell line registered a greater reduction in cell viability when compared to the A 549 cancer cell line." (PMID 32357523, 2020).
cancer (continued). "Interestingly, we also observed that carcinoma cell lines, expressing native forms of CEACAM-5 and CEACAM-6, showed a different profile for expression of the antigen recognized by NEO-201." (PMID 32637350, 2020). "In CEACAM6 KO cells the DNA damage response (DDR) is suppressed and there is also a significant decrease in the expression A3B, an intrinsic mutagen that contributes to cancer progression and metastasis." (PMID 31797958, 2019). "CEACAM6 is anchored to the cell membrane via a glycophosphatidylinositol (GPI) anchor at its C terminus and regulates cell adhesion, proliferation, signaling in cancer, and immunity." (PMID 31797958, 2019). "Staining of CEACAM6 was markedly stronger in cancer tissue than corresponding noncancerous hepatic tissue." (PMID 16868542, 2006). "CEACAM6 gene expression in cancer tissues was higher than in noncancerous tissues in 16 of the 23 cases; however, it was not statistically significant." (PMID 16868542, 2006). "Thus, CEACAM6 may be more effective than CEA as a marker for detecting early cancers and cancer relapse or metastasis." (PMID 25427744, 2015). "The question arises as to whether or not the positive correlation between CEA/CEACAM6 levels and tumors points to an instrumental role for these molecules in cancer." (PMID 18159236, 2007). "Furthermore, CEACAM6 was functionally involved in the initial steps of cancer progression and metastasis and may not be required for late-stage metastasis." (PMID 39468006, 2024). "This suggested that CEACAM6 may function as a negative immune checkpoint in cancer." (PMID 38279989, 2024). "Immunohistochemical analysis of PDX tumors confirmed that BRD4 was degraded by 84-EBET on both cancer and stromal cells in the tumors, suggesting that EBET diffused from the cancer cells had a bystander effect on CEACAM6-negative stromal cells." (PMID 38467634, 2024).